STAT3 (signal transducer and activator of transcription 3)
Diseases named in the same sentence as STAT3 in open-access papers (continued):
Sharing a sentence is not in itself a finding about the gene and the disease.
cancer (continued). "MiR-34a was largely reported to be a tumor suppressor via silencing multiple OS-related oncogenes and signaling pathways, including SIRT1, IGF2BP3, FOXM1/eEF2K and IL-6R/STAT3 signaling axis, regulated cancer drug resistance, growth and metastasis." (PMID 35081965, 2022). "In contrast, muscle mass and strength were preserved in cancer-related cachexia models, suggesting that STAT3 plays a more important role in disease than in the healthy state." (PMID 35328423, 2022). "Normally these cancers show upregulation of STAT3 and phosphorylation of STAT3 at Tyr705 and Ser727 and are partially sensitive to metformin, promoting a strong growth-inhibitory and apoptotic effect in these cells." (PMID 36672573, 2022). "STAT3 plays a key role in signal transduction pathways of cancer stem cells, and we found that MAL overexpression inhibited STAT3 phosphorylation in GC cells and MAL knockdown increased STAT3 phosphorylation." (PMID 35093120, 2022). "Application was also found to inhibit CSC markers, to modulate EMT markers, and to activate IL-6/STAT3 signalling, directly decreasing cancer cell invasiveness and migration." (PMID 35276890, 2022). "The development of specific and effective novel STAT3 inhibitors for potential cancer prevention and therapy is desirable." (PMID 36009550, 2022). "Accumulating evidence indicated that JAK2/STAT3 was closely correlated with cancer metastasis and progression 14-15." (PMID 35813296, 2022). "The mechanisms of STAT3 pathway regulation and the cancer hallmarks induced by the STAT3 pathway are also reviewed." (PMID 35356799, 2022). "We observed that LPS‐induced SMAR1 was able to regress the transcription of STAT3 also in cancer cells." (PMID 34689394, 2022). "On the other hand, STAT3 possesses oncogenic potential and contributes to cancer cell proliferation, anti-apoptosis, migration, invasion, immune suppression, stemness and resistance to chemotherapy." (PMID 35369073, 2022). "Previous research has developed a strong correlation between STAT3 activation and cancer development." (PMID 35928273, 2022). "As a result of examining the phosphorylation of JAK2 and STAT3, which are involved in the growth and death of cancer cells, phosphorylation was increased in the 5 μM S1P treatment group." (PMID 36500220, 2022). "STAT3 was most frequently found in S:E-specific cancer pathways, such as the JAK-STAT pathway, Notch signaling pathway, receptor tyrosine kinase/PDGF signaling pathway, TGF-β signaling pathway, and VEGFA signaling pathway." (PMID 36579559, 2022). "In cancer patients, the IL‐6/JAK/STAT3 pathway is highly up‐regulated and associated with muscle atrophy." (PMID 36127129, 2022). "The phosphorylation levels of p-LYN and p-STAT3 were found to be inhibited following minocycline treatment in these listed cancer cells." (PMID 35414768, 2022). "We observed that the AP3S1 overexpression was positively associated with many malignant pathways in pan-cancer, such as IL6 JAK STAT3 signaling, IL2 STAT5 signaling, TGF BETA signaling, interferon gamma response, and interferon alpha response." (PMID 35874816, 2022). "Compared with normal ovaries and benign tumors, JAK2/STAT3 is activated in high-grade OC and is involved in cancer progression and EMT." (PMID 36591515, 2022). "MiRNAs can dually induce/inhibit EZH2 in cancer cells to affect downstream targets such as Wnt, STAT3 and EMT." (PMID 35236381, 2022). "STAT3 hyperactivation was found in multiple myeloma, Hodgkin lymphoma, mantle cell lymphoma, and other cancers." (PMID 36366411, 2022). "The identification of a regulatory pathway from RNF7 to SOCS1/JAK/STAT3 is particularly exciting because STAT3 activation is widely observed in several human cancers." (PMID 35562668, 2022). "Altogether, piperlongumine can be considered as a promising anti-cancer bioactive agent that acts through the downregulation of c-Met, STAT3, NF-κB, PI3K/Akt, and ERK/MAPK signaling pathways, inhibition of GSTP1, and upregulation of hTRPV2." (PMID 36428575, 2022).
cancer (continued). "Ligation of IL-6 with IL-6R activates Janus kinase (JAK) tyrosine kinases leading to phosphorylation of signal transducer and activator of transcription 3 (STAT3), which is a well-studied cancer signaling pathway." (PMID 35924148, 2022). "As a well-known oncogenic transcription factor, STAT3 has been shown to activate the transcription of a few functional lncRNAs in human cancers." (PMID 35945579, 2022). "Another study demonstrated that STAT3 expression in the nucleus was connected to disease progression and lower cancer-specific survival." (PMID 36230984, 2022). "We also demonstrated that the effects of adiponectin and AdipoRon on cancer cells were due, in part, to suppression of the STAT3 signaling pathway as well as AMPK-pathway activation." (PMID 35121743, 2022). "Of note, STAT3 and mTOR can strongly regulate autophagy, a catabolic process articulated in different steps that, to some extent, also helps to preserve cancer cell integrity and to resist nutrient shortage." (PMID 35681760, 2022). "The bulk of evidence indicates that STAT3 significantly correlates with cancer development and immune escape." (PMID 36061181, 2022). "Wnt5 also controls IDO1 activity in DC via β-catenin signaling while maintaining continuous expression in several cancer cell lines via an AhR-IL-6-STAT3 (Signal Transducer And Activator Of Transcription 3) signaling loop, according to new research." (PMID 35918736, 2022). "Inhibition of Stat3 activation represses caspase-3 expression and the ubiquitin–proteasome system, thereby preserving muscle mass in cancer cachexia." (PMID 35812340, 2022). "STAT3, which is an essential intracellular signal transduction protein, can participate in the regulation of cancer cell proliferation, differentiation, apoptosis and invasion by acting on downstream related genes." (PMID 35414025, 2022). "As indicated by recent reports, STAT3-mediated lipid metabolism takes on a critical importance to cancer progression." (PMID 36106333, 2022). "Inhibition of HDACs results in activation of STAT3, which is overexpressed in cancer and regulates cancer formation, development and metastasis." (PMID 36235168, 2022). "SOCS2 was identified as a key direct target gene of miR-877-3p in GC, where miR-877-3p suppressed the expression of SOCS2 and promoted cancer cell stemness and chemoresistance subsequently by activating Jak2/Stat3 signaling." (PMID 35600882, 2022). "Considering that targeting the upstream signaling of HIF-1α is also a potential strategy in cancer therapy, we aimed to investigate the effect of co-targeting of STAT3 and AKT, which are upstream of HIF-1α function." (PMID 35236823, 2022). "TTI-101 has been demonstrated to successfully target STAT3 in several mouse models of inflammation and cancer." (PMID 36498596, 2022). "IL-6 signaling (mainly via the JAK/STAT3 signaling pathway in epithelial and immune cells) can promote chronic inflammation and cancer development (Johnson, O'Keefe and Grandis 2018)." (PMID 36313280, 2022). "The STAT3 signaling pathway plays a vital role in determining the outcome of the interaction between cancers and immune cells." (PMID 35563421, 2022). "For example, under hypoxia, increased p-STAT3 levels promote the nuclear translocation of PD-L1 in cancer cells, leading to the upregulation of GSDMC transcription." (PMID 35990696, 2022). "Like miR-21, aberrantly high levels of STAT3 in various malignancies are correlated with poor cancer prognosis." (PMID 35955412, 2022). "STAT3 target genes can improve the survival, proliferation, and immune evasion of early cancer cells." (PMID 35406557, 2022). "Taken together, these data suggest that LCN2 regulates protein expression related to cell survival and cancer progression mediated by NF-kB and STAT3 activation." (PMID 35470375, 2022). "Remarkably, STAT3 exerts a vital role in promoting cancer through regulating the activities of CSCs." (PMID 36557902, 2022).
cancer (continued). "Overall, these findings suggest that TXNIP has the potential to regulate STAT3 signaling in immune cells involved in cancer development." (PMID 36366411, 2022). "STAT3 and NF-κB activation and interaction are crucial in controlling cancer cell-inflammatory cell communication." (PMID 35745729, 2022). "PTAFR (platelet activating factor receptor) belongs to the G-protein-coupled receptor (GPCR) family with vital roles in cancer progression via regulating molecular pathways such as STAT3 and PI3K-AKT signaling networks." (PMID 35317831, 2022). "STAT3 activation affects proliferation, apoptosis, differentiation, angiogenesis, immune cell recruitment, and metastasis, all of which are cancer hallmarks." (PMID 36496998, 2022). "Among all STAT sub-members, STAT3 is the most important regulator of inflammatory factors that feed cancer progression." (PMID 35158821, 2022). "A variety of signaling pathways including TNF-α, KRAS, IL-6/JAK/STAT3, IL-2/STAT5, epithelial-mesenchymal transition, oxidative phosphorylation, and mTOR were found to be significantly associated with TRPs in pan-cancer." (PMID 35831825, 2022). "Recently, NB has been reported as a small molecule inhibitor of STAT3 which has been shown to suppress cancer stemness in several cancer types because STAT3 regulates the expression of proteins involved in cancer stem cell (CSC) self-renewal." (PMID 36180880, 2022). "The STAT-3 (signal transducer and activator of transcription-3) can facilitate cancer progression and metastasis via various signaling pathways." (PMID 35055094, 2022). "IL-6/JAK/STAT3 signaling acts to drive cancer cell proliferation, survival, invasiveness, and metastasis, while strongly suppressing antitumor immunity." (PMID 36221123, 2022). "More recently, studies have demonstrated that STAT3 activation, mediated by cytokines and oxidative stress, plays a central role in regulating skeletal muscle mass during cancer progression." (PMID 35847939, 2022). "In many human cancers, STAT3 is continuously activated, and the phosphorylation of specific tyrosine residue is an important step in STAT3 activation." (PMID 35463085, 2022). "Herein, forty-eight novel meridianin derivatives were obtained in this study, and JAK/STAT3 hyperactivated human cancer cell lines were evaluated." (PMID 35216314, 2022). "miRNA-124-3p inhibits the expression of PD-L1 by regulating STAT3 signaling pathway, and then promotes the anti-cancer response of CRC cells mediated by Tregs to inhibit tumorigenesis." (PMID 35574420, 2022). "Next, we analyzed the main signaling pathways that play a crucial role in the hallmarks of cancer such as the activation of STAT3 (Signal Transducer and Activator of Transcription 3), AKT (Protein Kinase B) and ERK (Extracellular signal-regulated Kinase)." (PMID 35365193, 2022). "Signal transducer and activator of transcription 3 (STAT3), is an important oncogenic protein that promotes cancer cell proliferation and survival, as well as controls cell cycle progression and resists apoptosis." (PMID 36034876, 2022). "The STAT3 phosphatase inhibitor STATTIC inhibited the cancer-promoting effect of NNMT overexpression on colony formation and migration in transwell experiments." (PMID 35851575, 2022). "Since STAT3 is known to directly regulate ICAM-1 expression in various cancer types, chromosome immunocompatibility (CHIP) assay was performed to investigate this role of STAT3 in CRC." (PMID 35487888, 2022). "The IL-6/JAK/STAT3 signaling has been shown to drive the proliferation, survival, invasiveness, and metastasis of cancer cells, while suppressing the antitumor immune response." (PMID 35102139, 2022). "According to our previous study, the cytoplasmic LMO2-LDB1 complex enhanced STAT3 activity to maintain CSC characteristics in cancer cells." (PMID 36359204, 2022).
cancer (continued). "Detailed mechanistic studies were performed that reveal that the anti-cancer effects were associated with the downregulation of the expression of VEGF, CYCLIN-D1, and STAT-3 genes and upregulation of the apoptotic Caspase-9 gene." (PMID 35216264, 2022). "Signal transducers and activators of transcription family 3 (STAT3) play a significant role in immune responses, cancer development, and cellular metabolism, in part by activating cytokine transcription." (PMID 35928250, 2022). "In future, the design and optimization of these oligonucleotide-based PROTACs, targeting oncogenic RBPs (e.g. IGF2BPs and YBX1) and DBPs (e.g. c-myc and STAT3), should be extensively investigated for targeted cancer therapy." (PMID 35410300, 2022). "STAT3 signaling also induces a cancer-promoting inflammatory environment by inducing the expression of inflammatory cytokines, chemokines, and other mediators." (PMID 35890318, 2022). "Further studies in different cancers will provide important information on the value of targeting macrophage-dependent STAT3 activity." (PMID 35053592, 2022). "Stattic, a small molecule inhibitor, abrogates STAT3 dimerization and translocation which eventually inhibits STAT3 activation in a phosphorylation-independent manner in many cancers." (PMID 35401182, 2022). "Since, in CRCs, FGFR4 mediates cancer progression via phosphorylation of STAT3, we assessed its phosphorylation status at the Y705 site in CRC cells after TRIP13 shRNA knockdown and treatment with DCZ0415." (PMID 35194944, 2022). "The synergy between p-STAT3 and IL6 in HER2+ BC promotes EMT and cancer stem cells proliferation; it is associated with trastuzumab resistance." (PMID 35248049, 2022). "Then, IL-6 activates the signal transducer and activator of the transcription 3 (STAT3) pathway in immune cells, stromal cells, and tumor cells, which supports the immune escape of cancer cells." (PMID 35884464, 2022). "JAK inhibitors, but not the β-adrenergic antagonist propranolol, correspondingly suppressed STAT3 phosphorylation in white adipose tissue while blocking adipose wasting in cancer cachexia murine models." (PMID 35785158, 2022). "Existing pharmacological studies showed that ALA exerted antitumor activity mainly by inhibiting the phosphorylation of signal transducer and activator of transcription 3 (STAT3) and affecting various key signal molecules involved in cancer progression." (PMID 35370661, 2022). "CAFs release high levels of IL-6 and TNF-α in an autocrine fashion upon STAT3 activation when co-cultured with cancer cells, promoting self-renewal and metastatic potential of cancer cells." (PMID 35443745, 2022). "Among them, we identified IL-6 as a proinflammatory cytokine that mediates the activation of Stat-3 in cancer cells, thus promoting tumorigenesis." (PMID 35625629, 2022). "The key mechanisms of immune invasion in cancer are the signal transducer and activator of transcription 3 (STAT3) pathway and myeloid suppressor cells (MSCs) [104, -106]." (PMID 36116940, 2022). "IL-8 has been involved in the maintenance of cancer stemness properties through the activation of STAT3." (PMID 35740546, 2022). "STAT3 also promotes Cyclin D1, c-Myc, and surviving expression to improve cancer cell proliferation and survival." (PMID 35799305, 2022). "Currently, STAT3 small molecule inhibitors and targeting strategies have shown anti-cancer activity in TNBC in vivo and in vitro." (PMID 35744786, 2022). "STAT3, as a signal transducer and transcription factor, plays an essential role in cancer malignancy." (PMID 36324587, 2022). "LDOC1 deficiency leads to enhanced IL-6/JAK2/STAT3 loop, through which LDOC1 mediates cancer progression." (PMID 36591515, 2022). "Given the increasing evidence supporting STAT3 as a pivotal target for cancer therapy, novel inhibitors targeting STAT3 will have a considerable inhibitory impact on cancers that harbor constitutively activated STAT3, such as TNBC." (PMID 36009550, 2022).
cancer (continued). "In this context, the therapeutic relevance of pyrimethamine in cancers characterized by frequent STAT3 activation is becoming more apparent." (PMID 34953855, 2022). "Previous study indicated that STAT3 was involved in the regulation of centrosome clustering in cancer cells." (PMID 36051696, 2022). "STAT3 is often de-regulated in several kinds of cancer and function as an onco-gene in tumorigenesis." (PMID 36557997, 2022). "STAT3 has a well-defined role in cancer development, acting in the VEGFA transcriptional activation, promoting angiogenesis." (PMID 34754096, 2022). "STAT3 and NF-κB pathways play an important role in the development and progression of cancer, and are closely related to proliferation, metastasis, and autophagy of HCC." (PMID 35139763, 2022). "This study indicates that lipid peroxidation regulates Tc9 cell longevity and antitumor effects via the IL-9/STAT3/fatty acid oxidation pathway and regulating T cell lipid peroxidation can be used to enhance T cell–based immunotherapy in human cancer." (PMID 35192544, 2022). "There is mounting evidence showing that STAT3 plays a crucial role in various diseases, such as cancer, cerebrovascular diseases, cardiovascular diseases, and obesity." (PMID 36557902, 2022). "The active JAK2 / STAT3 signaling pathway plays a vital role in the initiation and development of various cancers." (PMID 35883653, 2022). "On the other hand, inhibition of negative regulators such as PIAS3, SOCS1 and 3 and several cellular phosphatases (SHP1 and 2, PTPRD, PTPRT, PTPN1 and 2, DUSP22) can also lead to STAT3 activation in cancer." (PMID 35145111, 2022). "Taken together, these data revealed that the mTORC1/STAT3/miR-130b-3p/MBNL1 signaling cascade is also present in human cancer cells." (PMID 36217202, 2022). "Accordingly, the family of STATs, including STAT-3, is highly expressed and phosphorylated (activated) in a wide range of cancer cells and has an essential role in cell proliferation and survival." (PMID 35740967, 2022). "GO-Y30 modulated TGF-β and Treg function, supressed STAT3 in breast and pancreatic cancer cells, and inhibited the PD-1 immune checkpoint to increase the efficacy of cancer immunotherapy." (PMID 36700235, 2022). "STAT3, a protein that has been historically undruggable, is a transcriptional regulator allied with numerous cancers and other inflammatory and autoimmune disorders." (PMID 36499765, 2022). "We demonstrated that cancer-derived interleukin-6 (IL-6) stimulates STAT3-dependent, nuclear factor-κB-mediated indoleamine 2,3-dioxygenase (IDO) upregulation in eMDSCs which triggers immunosuppressive effects of eMDSCs." (PMID 36329699, 2022). "As the confluence point of multiple oncogenic signal pathways, STAT3 is found to be abnormally activated at high frequency in malignant tumors and is a promising molecular target for cancer therapy." (PMID 35154350, 2022). "Among the 7 STAT proteins, STAT3 activation plays important roles in cancer inflammation and immunity." (PMID 35890318, 2022). "Previous studies have shown that STAT3 can promote glycolysis metabolism of multiple malignant tumors by regulating the expression of glycolysis key enzymes and the glycolysis regulator." (PMID 36188586, 2022). "We further introduce the novel molecular mechanisms that we have identified to date involving STAT3 activation, cancer development, and malignant transformation." (PMID 36010693, 2022). "We have found that high level of STAT3 and STAT1 transcripts was associated with poor survival in patients through pan-cancer analysis." (PMID 35874683, 2022). "Various signaling pathways participate in the evodiamine-induced cancer cell apoptosis such as mTOR signaling, STAT3 signaling, and Bax/Bcl-2." (PMID 35899176, 2022). "We observed remarkably decreased Sox2 with either treatment, indicating that STAT3 maintains this marker of cancer stem cells." (PMID 34482626, 2022).